NFIB (nuclear factor I B)
Diseases named in the same sentence as NFIB in open-access papers (continued):
Sharing a sentence is not in itself a finding about the gene and the disease.
cancer (61 papers, 2010 to 2025). A tumor composed of atypical neoplastic, often pleomorphic cells that invade other tissues. "The results revealed a 25%–30% reduction in the expression of ABCB1 and ABCG2, which encode for P-glycoprotein and breast cancer resistance protein, respectively, in NFIB-overexpressed vs. control cells (P < .05)." (PMID 40554316, 2025). "It is known that NFIB is an oncogene, and, according to recent reports, its upregulation has been linked with the growth and progression of several types of cancer, including HCC." (PMID 37894381, 2023). "Given the association of high NFIB expression in group 3 tumors with poor survival, we showed that silencing NFIB expression dramatically decreased cancer cell proliferation, migration, and invasion in vitro." (PMID 34922631, 2021). "We then isolated an oncogenic target of miR-212-3p, i.e. NFIB, a nuclear transcription factor implicated in metastasis and recurrence in various cancers." (PMID 34922631, 2021). "The wide spread binding of NFIB in open chromatin sites has been linked to its regulatory action in adipocyte differentiation and cancer metastasis." (PMID 29765957, 2018). "It is logical to propose that NFIB-associated erroneous DNA replication and genomic instability might, at least partially, underlie the oncogenic potential of NFIB in various types of cancers, including SCLC." (PMID 37604829, 2023). "We also propose that cancer-associated NFIB overexpression/amplification could lead to replication alterations and genomic aberrations, eventually to the development of cancer." (PMID 37604829, 2023). "We identified significant downregulation of several metabolic pathways related to hepatic functionality, PPAR signaling, and drug metabolism for NFIB, NFIC, and NFIX, whereas pathways associated with cancer biology were significantly induced." (PMID 41106572, 2025). "We observed increased levels of CARM1, NFIB, and NFIBme2a as cancer progresses into malignant disease." (PMID 36690626, 2023). "NFIB is frequently amplified/overexpressed in many types of cancer and is defined as a “cancer-related gene”28." (PMID 37604829, 2023). "Our results showed that majority hub genes DCAF7, FGF2, GSK3B, NACC2, and NFIB were highly expressed and (nTPM >19) localised mainly in the nuclei of the cancer cells." (PMID 36468011, 2022). "In these cancers NFIB is thought to modulate chromatin structures to induce a stable epithelial-to-mesenchymal cell fate which is associated with the decreased expression of epithelial cell adhesion markers such as E-Cadherin." (PMID 35954220, 2022). "Again, in both NFIB-silenced and miR-212-3p stably-expressing cancer cells, substantially decreased numbers of spheres were noted." (PMID 34922631, 2021). "Given the direct inhibitory effect of miR-212-3p on c-Myc and NFIB’s promoting role in metastasis, we sought to study the effect of the miR-212-3p/NFIB axis on cancer stem cell (CSC) maintenance and self-renewal." (PMID 34922631, 2021). "With this prior evidence, we elucidated the oncogenic role of NFIB in group 3 MB cancer cells by studying the effect of silencing expression on proliferation, transwellmigration, and invasion." (PMID 34922631, 2021). "NFIB has been recognized as a TF that can either promote or suppress human cancers in a cancer-type dependent manner." (PMID 31847118, 2019). "The nuclear factor I (NFI) family members, especially NFIA and NFIB, play essential roles in cancers." (PMID 29577671, 2018). "Recent studies revealed that NFIs, especially NFIA and NFIB, also function in the development or progression of cancers." (PMID 29577671, 2018). "The identified downstream targets of miR-365 include cell division cycle 25A (CDC25A), cyclin D1 (CCND1), transcription termination factor 1 (TTF1), interleukin 6 (IL-6) and nuclear factor I B (NFIB) in various types of cancers." (PMID 28556798, 2017). "Contrary to MYB, the role of NFIB (Nuclear Factor I B) in normal and cancer cell biology remains obscure." (PMID 27533466, 2016).
cancer (continued). "Since a defined subset of GBM retains responsiveness to glial differentiation factors such as NFIB has important implications for the management of this cancer, as the ability to induce a more differentiated phenotype is a potential adjunctive therapy for GBM." (PMID 27083054, 2016). "Both NFIX and NFIB play a key role in development and cancer." (PMID 37817005, 2024). "NFIB is a transcription factor responsible of the correct development and regulation of cell differentiation in different tissues even if recent evidence suggested its key role in cancer." (PMID 38987822, 2024). "Besides SCLC, NFIB was also reported to be amplified in ER-negative breast cancer and esophageal squamous cell carcinoma, with possible oncogenic roles in these cancers." (PMID 36690626, 2023). "Thus, we wanted to independently test the role of NFIB R388 methylation in the regulation of cancer expansion." (PMID 36690626, 2023). "Interestingly, NFIB is the only member of the NFI family that is classified as “cancer-related genes” in the Human Protein Atlas." (PMID 37604829, 2023). "NFIB silencing reduced cancer cell proliferation, migration, and invasion." (PMID 34922631, 2021). "Therefore, the identification of a recurrent MYB:NFIB translocation in ACC offered a new opportunity to study MYB biology in a defined epithelial human cancer model system." (PMID 25587024, 2014). "However, NFIB can also act as oncogene in some other cancers." (PMID 24949940, 2014). "NFIB is a member of the nuclear factor I (NFI) family of transcription factors, with a cancer-specific role." (PMID 40943553, 2025). "We identified several TFs, including GTF2I, NFIB, NFATC4, ZNF37A, KLF13, and ZNF507, involved in cancer metastasis." (PMID 39273015, 2024). "We demonstrate that FOXA1 is an activator and NFIB is a repressor of SRR124–134 activity and SOX2 transcription in cancer cells, revealing a co-opting of the regulatory mechanisms involved in early development." (PMID 37738673, 2023). "NFIB and NFIX have been shown to act as either oncogenes or tumour suppressors across various cancers." (PMID 36569748, 2022). "By targeting NFIB, a well-studied metastatic driver, a regulator of EZH2, and downstream effector of c-Myc, miR-212-3p decreased cancer cell aggressiveness, stem cell maintenance, and renewal." (PMID 34922631, 2021). "Nuclear factor I/B (NFIB) participates in normal somatic development and recent studies have revealed its role in cancer progression and development." (PMID 32545648, 2020). "Alternately, ATAC-seq analysis of pure cancer cell populations of human small cell lung cancer (SCLC) identified a novel TF, nuclear factor I B (NFIB), which is necessary and sufficient to drive the metastatic ability of SCLC cells." (PMID 33385611, 2020). "NFIA, NFIB and NFIC expression levels were reduced in cancer tissues evaluated using mRNA HiSeq expression data from the TCGA database." (PMID 32219034, 2020). "miR-302a expression was decreased in most cancer tissues, which is consistent with the qPCR results, and NFIB and CD44 expression was increased in the corresponding cancer tissues compared with the matched adjacent normal tissues." (PMID 31754405, 2019). "To further elucidate the mechanism of NFIB down-regulation in CSCC tumors, we detected the expression of cancer-related genes." (PMID 24949940, 2014). "Moreover, the oncogenic potential of NFIB has been best studied in SCLC, where a number of groups described its role in cancer initiation and metastasis using genetically engineered mouse models and human patient specimens." (PMID 37604829, 2023). "Like NFIB, CARM1 is often overexpressed in human cancers, including lung cancer." (PMID 36690626, 2023).
cancer (continued). "This confirms the repressive effect of NFIB over SOX2 expression and illustrates a potential mechanism upstream of SOX2 that modulates chromatin accessibility at the SRR124–134 cluster and subsequent control of SOX2 transcription in cancer cells." (PMID 37738673, 2023). "In humans, NFIB and NFIX have been related to human development and cancer." (PMID 36569748, 2022). "Fortunately, we found three potential binding sites on PINK1 gene promoter for NFIB, and bioinformatics analysis revealed that PINK1 was enriched in focal adhesion and pathways in cancer." (PMID 33981484, 2021). "NFIA and NFIB were expressed if any only in basal cells of normal esophageal epithelia, mainly located in the nucleus, while in ESCC tissues, NFIA was highly expressed in cancer cells, located in both the nucleus and cytoplasm." (PMID 29577671, 2018). "Furthermore, we identified cancer-related genes aberrantly expressed in ccRCC (BRMS1L, CPEB3, DNAJB9, KIF3B, NFIB, PTPRJ, RBL2) and targeted by members of the miR-106b-25 cluster, suggesting that their dysregulation may be driven by these miRNAs." (PMID 40943553, 2025). "We further confirmed that CARM1i phenocopies genetic ablation of CARM1 and NFIB methylation in H69 and CORL47 cells and that inhibitor does not exert an unspecific effect on cancer cells growth." (PMID 36690626, 2023).
bacterial infection (1 paper, 2022). "Although there is no previous studies directly proving that NFIB is directly related to bacterial infection, the results obtained right now were reasonable and explainable." (PMID 35409172, 2022).
NFIB also shares sentences with these, for which no sentence is quoted: mucoepidermoid carcinoma (7 papers); infection (5); cylindromas (4); salivary gland tumors (3); alveolar rhabdomyosarcoma (2); non-small cell lung carcinoma (2); salivary carcinomas (2); schizophrenia (2); sinonasal carcinoma (2); spiradenoma (2); adenocarcinoma (1); adenosarcoma (1); autoimmune disease (1); brain cancer (1); breast adenocarcinoma (1); breast adenoid cystic carcinomas (1); breast tumors (1); B‐cell lymphoma (1); chronic lymphocytic leukemia (1); chronic myelogenous leukemia (1); connective tissue tumors (1); desmoplastic small round cell tumor (1); endometritis (1); esophageal squamous cell carcinoma (1); follicular lymphoma (1); glomerulonephritis (1); hairy cell leukemia (1); hidradenocarcinoma (1); hidradenoma (1); HIV-1 infection (1).
A further 28 diseases each share a sentence with NFIB in 1 paper.